THBS2 (thrombospondin 2)
Diseases named in the same sentence as THBS2 in open-access papers (continued):
Sharing a sentence is not in itself a finding about the gene and the disease.
tumor (continued). "PEDF is generally considered a tumor suppressor, while for THBS1 and THBS2, controversial roles in cancer have been reported." (PMID 38339060, 2024). "As depicted in UMAP plots, THBS2, THBS4 and COMP were primarily expressed by fibroblasts, while THBS3 was predominantly expressed by tumor cells and fibroblasts, and THBS1 was predominantly expressed by fibroblasts, monocyte-macrophages and endothelial cells." (PMID 38827236, 2024). "KEGG analysis indicated that ADAMTS2, COL12A1, and THBS2 are closely related to ECM, and ECM plays an important role in tumor metastasis and progression." (PMID 35879877, 2023). "In this study, the interaction between THBS2 and GPR132 was assessed in an immunosuppressive tumour microenvironment." (PMID 37884956, 2023). "Genes such as COL14A1, COL6A1, THBS2, COL4A2 and COL11A1 are involved in tumor migration and invasion." (PMID 37024829, 2023). "The tumor volume and weight of mice bearing sh-AGAP2-AS1-treated ACHN cells were significantly reduced; however, those were increased following further oe-THBS2 treatment." (PMID 38110984, 2023). "SOSTDC1, TLR5, MT1G, and MUC6 were downregulated in locally advanced tumor tissue samples, whereas COL8A1 and THBS2 were upregulated (P<0.05)." (PMID 36969001, 2023). "Upon delivery, miR-598 targeted and inhibited the expression of THBS2, which inhibited the proliferation, migration, and invasion of NSCLC cells in vitro, while arresting tumor growth and metastasis in vivo." (PMID 36609437, 2023). "THBS2 expression was strongly correlated with tumour purity in THCA, COAD, READ, LICH and KICH, whereas it was negatively correlated with tumour purity in THCA, DLBC, LGG and GBM." (PMID 37884956, 2023). "Tumor size-related proteins were involved in angiogenesis (VCAN, VTN, NRP1), EMT (FN1, CD44, THBS2), and translation (EIF1AX, EIF5), further indicating the biological basis of ccRCC growth." (PMID 37460463, 2023). "The results revealed that SPP1, COMP, THBS2, SERPINE1, and COL11A1 were highly expressed in tumor tissues, while MYH11, TAGLN, and CNN1 were lowly expressed." (PMID 36999888, 2023). "In addition, a subcutaneous xenograft tumor model, a nude mouse intraperitoneal metastasis model, and a tail vein injection metastasis model were constructed to evaluate the effects of BMSC-derived MVs and THBS2-deficient BMSC-derived MVs on GC development and metastasis in vivo." (PMID 37798762, 2023). "In particular, THBS2 was considerably downregulated in KICH and UCEC and upregulated in other tumour types including COAD." (PMID 37884956, 2023). "Of the overlapping set of proteins, the levels of WFDC2, S100P, CD55, MDK, THBS2, and MFAP2 were more than 2-fold higher in PDAC compared with tumor-adjacent tissue in our data." (PMID 36923555, 2022). "We then analyzed pan-cancer THBS2 expression and that in normal tissues using GEPIA2, which contains data for 31 tumor tissues from the TCGA database, as well as that of their corresponding normal tissues in the GTEx database." (PMID 35701829, 2022). "Strikingly, we observed that 6 out of 10 tumor-draining lymph nodes samples had proportions, albeit heterogeneous, of metastatic LUAD cancer cells that were THBS2 positive (Figure." (PMID 35547750, 2022). "Then, CAF-derived THBS2 binds to its cognate receptors integrin αvβ3/CD36, leading to the activation of MAPK pathway to promote tumor growth." (PMID 35547750, 2022). "Our results showed that the hub genes COL1A1, THBS2, and SPP1 were also able to alter cellular components in the tumor microenvironment, and that they had an axial relationship with PD-L1 expression." (PMID 33345281, 2021). "Several potential biomarkers have been recently described such as a three-protein panel in urine, Galectin-1 (Gal-1) in serum, thrombospondin-2 (THBS2) in plasma, circulating tumor DNA (ctDNA), and the IMMrayTM PanCan-d 29 biomarker signature in serum." (PMID 33807330, 2021).
tumor (continued). "THBS2 is recognized as an ECM-modifying enzyme and functions as a suppressor of tumor growth and angiogenesis by interacting with matrix serine proteases and MMPs in numerous cancers." (PMID 34471634, 2021). "For example, the high expression of THBS2 and COL1A2 facilitated GC proliferation and invasion but inhibited tumor apoptosis through the PI3K-Akt signaling pathway." (PMID 33080572, 2020). "After establishing an orthotopic tumor model through the injection of tumor cells into the cecum of BALB/c nude mice, we discovered that THBS2 knockdown or overexpression obviously inhibited and accelerated tumor growth." (PMID 33244454, 2020). "The violin plot showed the metastasis-related genes were higher expression in LUAD tumor tissues, but only LAMC2, THBS2, ITGB4, COL1A1 and FLNC showed positively correlated with poorer survival of LUAD and the expression level of GPR115." (PMID 33330053, 2020). "In total, we quantified approximately 4200 proteins and found that mucinous (e.g. MUC1 and MUC2) and mesenchymal proteins (such as THBS2, COL11A1, and CTHRC1) were significantly upregulated in the primary tumor compared to healthy surrounding tissue." (PMID 29901861, 2018). "In our dataset evidence of inflammation comes from the increased levels of THBS2 and SPARC in the tumor stroma that are both induced by IL1β in fibroblasts in vitro." (PMID 29176937, 2017). "In our previous study, THBS2, COL11A1 and VACN were also identified as up-regulated genes in NSCLC compared with adjacent non-tumor tissues through integrated analysis of microarray data." (PMID 28881680, 2017). "We further detect THBS2 protein expression level of 100 CRC tissue samples including 10 paired cases with both normal and tumor samples by immunohistochemistry (IHC)." (PMID 27632935, 2016). "Expression microarray analysis of transfected cells revealed transcriptional upregulation of thrombospondin 2 (TSP2), a tumor growth inhibitor, acting principally through counteracting angiogenesis." (PMID 19912643, 2009). "Furthermore, activated CAFs release SDF-1/CXCL12, OPN, periostin, galectin, THBS2, MFGE8, and diverse cytokines such as IL-6 and IL-32, which promote the EMT, tumor invasion, and tumor metastasis." (PMID 40352270, 2025). "This suggested that the ligand-receptor interactions between THBS2 and ITGB1 might play a regulatory role in spatial communication between tumor cells and other cell types." (PMID 40688093, 2025). "We also observed increased expression of proteoglycans such as CTHRC1 and THBS2 that were unique to myCAF, which have both been determined to contribute to EMT through the Wnt/b-catenin and NF-kB pathways, leading to tumor invasiveness and poor survival." (PMID 39075108, 2024). "Most importantly, in mouse xenograft experiments with CCLP1, an established human cell line of iCCA, the simultaneous presence of blocking antibodies for THBS1, THBS2, and PEDF in the iCCA ECF was able to drastically reduce the tumor growth and the extent of tumor infiltration in local lymph nodes." (PMID 38339060, 2024). "The results showed that overexpression of THBS2 did not significantly alter tumour volume in GPR132-KO mice." (PMID 37884956, 2023). "We conclude that CC tumor cells show ectopic expression of FOXQ1 and THBS2 possibly making these tumor cells independent of fibroblast cell support." (PMID 38156105, 2023). "On the other hand, upregulation of THBS2 (Thrombospondin2) was detected in liver metastases of UM or CRC and might serve as a prognostic biomarker for both tumor entities." (PMID 37179302, 2023). "In GPR132-KO mice, overexpression of THBS2 neither altered tumour volume nor affected the abundance of tumour-infiltrating CD8 + T cells and exhausted CD8 + T cells." (PMID 37884956, 2023). "Immuno-morphometry revealed that 30–40% of the tumor cells expressed FOXQ1, MMP11, and THBS2." (PMID 38156105, 2023).
tumor (continued). "The most enriched glycoproteins in tumour ECM compared to non-tumour ECM included thrombospondin-2 (16.9-fold), MXRA5 (14.4-fold), peroxidasin (2.5-fold), thrombospondin-1 (2.5-fold), SPARC (2.3-fold), FRAS1 (2.3-fold) and tenascin-C (2.1-fold)." (PMID 37397358, 2023). "Moreover, overexpressed THBS2 influenced the M2 polarisation of macrophages by interacting with GPR132, thereby affecting immune cell infiltration in the tumour microenvironment." (PMID 37884956, 2023). "Although THBS2 has been reported to be involved in some specific tumours, no studies have reported a systemic pan-cancer analysis of THBS2 to date." (PMID 37884956, 2023). "Mir-20a targets the thrombospondin 2 (THBS2) gene, which codes for a matricellular glycoprotein involved in the regulation of multiple biological processes, which has been characterized alternately as a tumor suppressor or as an oncogenic factor." (PMID 35456001, 2022). "Finally, THBS2 recombinant protein suppressed ex vivo T cells proliferation and promoted in vivo LUAD tumor growth and distant micro-metastasis." (PMID 35547750, 2022). "Thrombospondin-2 did not provide additional value to CA 19-9 in differentiating the benign disease group; however, heterogeneity was notable in the benign cohort." (PMID 34319497, 2022). "In this study, THBS2 expression did not correlate with tumor purity and showed significant positive correlation with infiltrating levels of B cell, CD4+ T cell, CD8+ T cell, macrophage, neutrophil, and dendritic cells in TIMER 2.0 database." (PMID 34471634, 2021). "Thus, we chose THBS2 as a representative to further explore the roles of THBS2 in EMT and tumor metastasis by cellular experiments." (PMID 34804159, 2021). "Our in silico study reveals that an abundance of COL11A1 mRNA could induce the transcriptional upregulation of THBS2, COL10A1, COL5A2, and COL1A2 genes cooperatively, to promote the neoplasia." (PMID 33597969, 2021). "Among them, 13 proteins correlated with clinicopathological parameters and of these proteins, eight proteins were identified in neoplastic islands (ACTR2, CSTB, COL1A2, LTA4H, PGK1, NDRG1, S100A8, S100A9) and five proteins were identified in tumor stroma (COL6A1, FSCN1, ITGAV, MB, THBS2)." (PMID 30185791, 2018). "Furthermore, a negative correlation was found between the expression of THBS2 and hsa-miR-203a-3p; thus, THBS2 was considered as a target gene responsible for tumor progression and angiogenesis." (PMID 41226545, 2025). "Indeed, THBS2 and TAGLN expression was higher in the samples with low tumor cellularity, inferring at least some expression may be due to the higher stromal content of the samples." (PMID 36222710, 2022). "A proteomic analysis of colorectal normal and tumor ECM revealed that collagen IV, V and XIV, fibrilin, emilin, vitronectin, laminin and endomucin have increased expression in tumor ECM, and that periostin, versican, thrombospondin-2 and tenascin were exclusively present in tumor tissue." (PMID 35053521, 2022). "Thus, THBS2 might promote cancer progression by remodeling the TME, affecting CD47-mediated signaling pathways, activating the pro-tumor functions of ADAMTSs, and enhancing MMP-2 expression." (PMID 35701829, 2022). "Therefore, we investigated whether the expression of THBS2, FSTL3, TNNT1, BGN, CTHRC1, and NOX4 was correlated with immune cell infiltration levels in CRC via the Tumor Immune Estimation Resource (TIMER) database." (PMID 35127707, 2021). "Finally, thrombospondin 2 (TSP2) secreted by endothelial cells maintains solitary DTCs in a dormant state, while TGFβ1 and periostin (POSTN) promote dormancy exit, leading to an increase in tumor size and recurrence." (PMID 32260071, 2020). "Our data demonstrated that the postoperative level of THBS2 in NSCLC patients underwent tumor resection decreased significantly, which suggests that high level of THBS2 in peripheral blood are probably derived from the tumor tissue itself, as have been reported." (PMID 31296790, 2019).
tumor (continued). "The fact that FOXQ1 and THBS2 are not expressed or expressed at very low levels in immune cells should make these two markers suitable for LN analysis, which has proved to be superior to analysis of primary tumor for prediction of outcome by molecular techniques." (PMID 38156105, 2023). "PEDF is not expressed by the iCCA cells, whereas THBS1 and THBS2 are expressed and released in the iCCA TME by both tumor cells and CAFs." (PMID 40001923, 2025). "The data obtained from these tumours are also consistent with an upregulation of anti-angiogenic ING4 mRNA levels in the human xenograft tumours in vivo, with no significant changes are detected for ANG, VEGFA, HIF1α, THBS2 and COL18A1." (PMID 35513564, 2022).
cancer (134 papers, 2002 to 2026). A tumor composed of atypical neoplastic, often pleomorphic cells that invade other tissues. "THBS2 is a member of the calcium-associated glycoprotein family and is also overexpressed in multiple cancers including PDAC." (PMID 40897818, 2025). "T1 and T2 clusters exhibited similar marker genes, including POSTN, COMP, and THBS2, which are markers associated with cancer-associated fibroblasts, showing heightened expression." (PMID 39670859, 2025). "THBS2 has been reported to act as a diagnostic and prognostic biomarker and be associated with cancer progression and recurrence in several cancer types." (PMID 39732719, 2024). "In this study, we comprehensively and thoroughly investigated the transcriptome characterizations of THBS family genes at the pan-cancer level, indicating that THBS2 was positively associated with CAFs, EMT, and chemoresistance." (PMID 39732719, 2024). "Based on OS, DSS, DFI and PFI data, survival was compared between the THBS2-mutation and non-THBS2-mutation groups in pan-cancer." (PMID 37884956, 2023). "In particular, THBS2 expression was positively associated with the proportion of memory T cells, NK cells and regulatory T cells in pan-cancer and negatively associated with the proportion of activated CD8 T cells in CHOL, DLBC, MESO and TGCT." (PMID 37884956, 2023). "The cBioPortal database was used to analyse THBS2 mutations and evaluate the frequency of various mutation types in pan-cancer." (PMID 37884956, 2023). "Overexpression of THBS2 is associated with cancer progression and metastasis in GC and can be used as a biomarker in predicting the clinical outcome of GC patients." (PMID 37361568, 2023). "Abundant THBS2 expression was associated with a worse OS in all of these types of cancer except SKCM." (PMID 35701829, 2022). "THBS2 expression has been linked to immune and stromal scores and immune checkpoint markers in various cancers." (PMID 35701829, 2022). "THBS2 was significantly overexpressed in 17 of the 33 investigated cancers and linked to a poor prognosis in pan-cancer survival analysis." (PMID 35701829, 2022). "Kaplan–Meier curves associated increased THBS2 expression with a poor prognosis for these seven types of cancer." (PMID 35701829, 2022). "Thrombospondin-2 (THBS2) is a type of secreted protein that has been found to be a diagnostic biomarker in a variety of cancers." (PMID 34659407, 2021). "In the present study, we employed versatile public databases to assess the expression and mutations of different THBSs in pan-cancer and performed functional experiments to analyze the roles of THBS2 in gastrointestinal cancer metastasis." (PMID 34804159, 2021). "THBS2 was upregulated in COAD, GBM, KIRC, KIRP (kidney renal papillary cell carcinoma), PAAD, STAD, and TGCT, and overexpression of THBS2 was associated with shorter survival in these cancers." (PMID 34804159, 2021). "THBS2 has been found to have both pro- and antitumorigenic functions and an association with both good and poor prognosis has been found in different cancers." (PMID 32887625, 2020). "Further study on the mechanism underlying the activity of THBS2 is warranted to have further implications for cancer diagnosis and treatment of pulmonary AC." (PMID 27513329, 2016). "Secondly, given THBS2's prominent role in differential expression, correlation analysis, functional enrichment, and cell trajectory analyses, this study primarily focused on exploring the association between THBS2 and cancer-associated fibroblast function." (PMID 38827236, 2024). "Mutations in the THBS2 gene in mice increased susceptibility to cancer." (PMID 35879877, 2023). "Moreover, THBS2 was identified as a potential key regulator and therapeutic target associated with this cancer type." (PMID 36969001, 2023). "We investigated whether THBS2 expression is associated with patient prognosis in pan-cancer analysis (OS, DSS, DFI, and PFI)." (PMID 35701829, 2022).